IGF1 (insulin like growth factor 1)
Diseases named in the same sentence as IGF1 in open-access papers (continued):
Sharing a sentence is not in itself a finding about the gene and the disease.
ovarian carcinoma (continued). "PON-2, an antioxidant protein, has a protective role in ER stress from apoptosis, and overexpression of PON-2 inhibits tumor development by inhibiting insulin-like growth factor-1 (IGF-1) expression and signaling in ovarian cancer cells." (PMID 33182770, 2020). "Further basic research manifested the IGF1 promoted the proliferation and migration of ovarian cancer cells and inhibition of IGF1 receptor and the downstream molecules effectively suppressed the malignant phenotype of tumor cells." (PMID 33102229, 2020). "Seven serum starved ovarian cancer cell lines were stimulated with IGF-1 or HRG for 15 minutes, and then downstream signaling cascades were assessed via western blot." (PMID 31728045, 2019). "A panel of ten ovarian cancer cell lines was stimulated with IGF-1 or HRG and proliferation was assessed via Cell Titer-Glo® Luminescent Cell Viability assay after 72 hours." (PMID 31728045, 2019). "We found that the PI3K/AKT/mTOR pathway, a downstream signaling pathway of IGF-1, was more strongly activated by the intake of animal protein (casein) than the intake of plant protein (soy protein) in mice with ovarian cancer." (PMID 31284691, 2019). "For example, 17β-estradiol (E2), progesterone (P4), and insulin-like growth factor 1 (IGF-1) have all been proposed to influence ovarian cancer development." (PMID 29603059, 2018). "Consistent with previous data, we observed mitogenic activity after treatment of epithelial ovarian cancer cells with E2 and IGF-1." (PMID 29603059, 2018). "Utilizing molecular, biochemical, and immunological approaches, we demonstrate that PON2 decreases ovarian cancer cell proliferation by regulating both IGF-1 expression as well as IGF-1 signaling." (PMID 29531225, 2018). "We demonstrated the antagonistic effect of adiponectin on E2- and IGF-1-induced epithelial ovarian cancer cell proliferation." (PMID 29603059, 2018). "It has been have clearly demonstrated that IGF1/mTOR pathway took part in promoting cell proliferation and affecting chemo-response in ovarian cancer." (PMID 29910195, 2018). "Taken together, these findings indicate that adiponectin represses the proliferation of epithelial ovarian cancer cells and reverses the stimulatory effects of E2 and IGF-1 on cell proliferation by downregulating the expression of their receptors." (PMID 29603059, 2018). "Previous studies reported E2, P4, and IGF-1 to affect ovarian cancer development, which prompted us to examine the effects of adiponectin and E2, P4, or IGF-1 on the proliferation of cancer cells." (PMID 29603059, 2018). "Lau and Leung59 have identified that PI3K/Akt/mTOR is required for insulin-like growth factor 1-induced E-cadherin down-regulation and up-regulation of E-cadherin transcriptional repressors, Snail and Slug, in human ovarian cancer cells." (PMID 28900284, 2017). "For example, elevated IGFBP-2 and reduced IGF-1 levels or high levels of an IGFBP-2/IGF-1 ratio were shown to stratify an ovarian cancer patient subgroup with poor prognosis." (PMID 28143425, 2017). "Both insulin-like growth factor 1 (IGF1) and 2 are growth hormone mediators that have a significant role in cell growth and are overexpressed in ovarian cancer." (PMID 27594911, 2016). "For example, elevated IGF1 and IGF2 expression were linked to disease progression and poor survival in ovarian cancer." (PMID 26861122, 2016). "In a previous study, we showed that a high energy diet (HED) was associated with extensive ovarian tumor formation, elevation of insulin, insulin growth factor (IGF-1) and higher levels of inflammation markers in an isogeneic mouse model of ovarian cancer." (PMID 25895126, 2015). "One study demonstrated that IGF-1 in human ovarian OVCAR-3 cells enhanced the expression of KCl cotransport (KCC) and was associated with proliferation and invasiveness of ovarian cancer cells." (PMID 25866823, 2015).
ovarian carcinoma (continued). "It has been reported that the expression of IGF-1 mRNA in human ovarian cancer cells is directly related to the expression of COX-2 mRNA." (PMID 25999995, 2015). "Indirect effects of AMPK results in attenuation of the insulin/IGF-1 pathways, which are known to be upregulated in many cancers including ovarian cancer." (PMID 25895126, 2015). "In ovarian cancer, multiple reports have shown high levels of IGF-1 in cancer cells and in blood, along with increased expression of its receptor." (PMID 25026276, 2014). "OVCAR5, an immortalized ovarian cancer cell line, were found to be sensitive to IGF1, with the dose of IGF1 (i.e., the total mass of IGF1 available) a more reliable predictor of cell response than ligand concentration." (PMID 25115504, 2014). "Previous studies on the role of IGF1 in ovarian cancer show that elevated serum levels of IGF1 are often observed in this cancer." (PMID 24237932, 2013). "Primary cancer cells from patients with advanced epithelial ovarian cancer produced endogenous IGF-1, grew autonomously and proliferated in SFM." (PMID 24103397, 2013). "Taken together, these data indicate that the IGF-1/IGF-1R system has a prominent role in the proliferation of human epithelial ovarian cancer cells." (PMID 24103397, 2013). "A recent in vitro study indicated the role of IGF1 in enhancing ovarian cancer cell proliferation through PI3K/Akt/mTOR signalling." (PMID 24237932, 2013). "Gene expression analysis in these two highly homogeneous groups of patients indicates the potential role of IGF1 as one of the key signalling pathways involved in the development of intrinsic chemotherapy resistance in ovarian cancer." (PMID 24237932, 2013). "We report that the ovarian cancer cells from patients with advanced EOC produce endogenous IGF-1, express IGF-1R and grow autonomously in serum-free media (SFM)." (PMID 24103397, 2013). "Downregulation of PTK6 also prevented IGF-1 stimulated anoikis resistance of DOV-13 ovarian cancer cells, which co-express PTK6 and IGF-1R." (PMID 20668531, 2010). "Apelin suppresses the proliferative effect of estrogen on epithelial (OVCAR-3) ovarian cancer cell lines and insulin-like growth factor 1 (IGF-1) on granulocyte (COV434) ovarian cancer cell lines by the interaction of the apelin receptor with those hormones’ receptors." (PMID 40076482, 2025). "The potential clinical implications are supported by the finding that serum levels of IGF-1, IGF-2, and PAPP-A2 are associated with patient prognosis and may find use as biomarkers for ovarian cancer." (PMID 38396692, 2024). "Our exercise intervention among women with ovarian cancer resulted in changes in two prespecified biomarkers in the exercise group compared to the attention‐control group, a 57.4% reduction in serum leptin and a 14.9% reduction in IGF‐1." (PMID 37269192, 2023). "In addition, The Cancer Genome Atlas (TCGA) database analysis revealed a putative relationship between WISP1 and insulin growth factor-1 (IGF1) in ovarian cancer." (PMID 35964060, 2022). "In addition, silencing of IGF1 increased the expression of epithelial markers and downregulated that of mesenchymal markers in CAOV4 cells, illustrating that silencing of IGF1 exerted inhibitory effect on EMT of ovarian cancer cells." (PMID 35964060, 2022). "In addition, the results of UALCAN database showed that the expression of IGF1 was increased over the clinical staging of ovarian cancer." (PMID 35964060, 2022). "Therefore, we inferred that the expression of IGF1 in ovarian cancer was significantly related to EMT signaling pathway." (PMID 35964060, 2022). "The effect of IGF1 on biological functions of ovarian cancer cells was investigated in SKOV3 cells." (PMID 35964060, 2022). "This study intended to clarify the mechanisms by which WISP1-mediated IGF1/αvβ3/Wnt axis might affect the progression of ovarian cancer." (PMID 35964060, 2022). "RT-qPCR and IHC showed increased IGF1 expression in ovarian cancer tissues." (PMID 35964060, 2022).
ovarian carcinoma (continued). "We then pinpointed the effect of endogenous IGF1 on ovarian cancer cell biological functions." (PMID 35964060, 2022). "However, the mechanism by which WISP1 affects EMT in ovarian cancer involving the interplay with IGF1 is still poorly understood, which attracted our attention." (PMID 35964060, 2022). "Moreover, the obtained findings here proved that WISP1 was positively correlated with IGF1, which was also upregulated in ovarian cancer tissues, and IGF1 promoted malignant characteristics of ovarian cancer cells." (PMID 35964060, 2022). "Finally, ovarian cancer nude mouse models were prepared to unveil the in vivo effects of WISP1/IGF1." (PMID 35964060, 2022). "Furthermore, the IGF1 receptor (IGF1R), which mediates the biological actions of IGF1, is overexpressed in most tumors and cancer cell lines, including ovarian cancers." (PMID 34220714, 2021). "It is well documented that high IGF1 levels are significantly associated with early-stage cancer, nonserous histology, and optimal cytoreduction in epithelial ovarian cancers." (PMID 34422647, 2021). "The reduction of IGF-1 would weaken the mitogen effects on the pathogenesis of ovarian cancer." (PMID 31284691, 2019). "We also analyzed the serum and ascites levels of insulin and IGF-1 in mice with ovarian cancer." (PMID 29844867, 2018). "Clinical studies suggest a role for IGF-1 in ovarian cancer etiology." (PMID 29531225, 2018). "How does PON2 reduce IGF-1 levels and cell proliferation in ovarian cancer cell lines?" (PMID 29531225, 2018). "Next, we investigated whether ovarian hormones and a growth factor (E2, P4, and IGF-1) could affect adiponectin activity in epithelial ovarian cancer cells." (PMID 29603059, 2018). "How does PON2 reduce IGF-1 signaling in ovarian cancer cells?" (PMID 29531225, 2018). "The reduction of IGF-1 would weaken mitogenic effects on the pathogenesis of ovarian cancer." (PMID 28665326, 2017). "In addition, reduced IGF-1 serum levels have been reported in epithelial ovarian cancer and lower IGF-1 mRNA levels have been observed in HCC compared to corresponding non-malignant liver tissues." (PMID 28143425, 2017). "IGF-1 has been confirmed to enhance growth of ovarian cancer cell." (PMID 28261315, 2017). "IGF-1 is overexpressed in pancreatic, colon, breast, and ovarian cancers." (PMID 27683110, 2016). "In addition to comparing baseline variation between the cell lines, we determined how these behaviors changed in response to four growth factors implicated in ovarian cancer progression: HB-EGF, NRG1β, IGF1, and HGF." (PMID 26648788, 2015). "In ovarian cancer, an elevated serum level of IGF-1 is often observed." (PMID 26360832, 2015). "Thus, we hypothesized that elevated IGF1 levels within the ovarian cancer tumor microenvironment attenuate apoptosis of detached cancer cells, thereby promoting peritoneal metastasis." (PMID 41463024, 2025). "In summary, we found that a 6‐month home‐based exercise intervention in women with ovarian cancer resulted in a reduction in leptin and IGF‐1 levels which may have a beneficial effect on cancer‐related outcomes, but also an increase in circulating levels of VEGF." (PMID 37269192, 2023). "Here, this study aimed to explore whether IGF1 also affects ovarian cancer." (PMID 35964060, 2022). "Therefore, targeting the IGF1 pathway may be promising for the treatment for ovarian cancer patients with liver metastases." (PMID 33102229, 2020).
ovarian carcinoma (continued). "Specific neutralizing antibodies directed against four agents known from the literature to cause EMT—that is, EGF, HGF, IGF-1, and TGF-β1—were added to the malignant ascites to establish whether some of these agents may be responsible for EMT development in ovarian cancer cells." (PMID 30609691, 2019). "Finally, we investigated whether E2, P4, and IGF-1 can regulate AdipoR1 and AdipoR2 expression and modulate the effects of adiponectin on the proliferation of ovarian cancer cells." (PMID 29603059, 2018). "How these proteins relate to the effect of LO remains to be uncovered, but a hint may lie in a previous report where genetic down-regulation of PAPPA by a protease inhibitor reduced ovarian cancer cell growth, invasion and metastatis via suppression of IGF-1-dependent Akt and ERK1/2 activation." (PMID 26161641, 2015). "The genetic instruments for IGF-1 were not available in the GWAS for ovarian cancer, invasive mucinous ovarian cancer, or endometrioid ovarian cancer, and no suitable proxy SNPs were available, meaning the causal effect of IGF-1 on these cancers could not be estimated." (PMID 40987470, 2025). "The current study developed a predictive model of CSOARG for prognosis in ovarian cancer using eight key genes (WNK1, ANGPTL4, AREG, IGF1, CXCL10, GMPR, FANCB, LYG1)." (PMID 40510161, 2025). "As shown in ovarian cancer cell lines, E2 induces gene expression of IGF-1 and c-myc and increases the binding of ERα to the promoters of IGF-1 and c-myc." (PMID 36729355, 2023). "IGF1 and WISP1 expression was elevated in ovarian cancer tissues and cells, which shared correlation with poor prognosis of ovarian cancer sufferers." (PMID 35964060, 2022). "For example, in cell cultures for ovarian cancer, VASH1 is able to inhibit insulin-like growth factor 1 (IGF-1) expression and inhibit its angiogenesis." (PMID 36504559, 2022). "KRAS and IGF1 are the top activated signaling, along with WNT1 inhibited, in immunotherapy responded ovarian cancer." (PMID 34921236, 2021). "In a previous study, we found that IGF1 activates mTOR and limits the antitumor activity of BYL719 in breast and ovarian cancers." (PMID 34067117, 2021). "We have previously developed a computational model of the interactions between IGF1, IGF1R, and IGFBPs in ovarian cancer cells." (PMID 26861122, 2016). "Other studies have also shown that IGF-1 and IGFBP-2 in human ovarian cancer cell lines resulted in the induction of proliferation and invasion through phosphorylation of AKT and ERK1/2." (PMID 25866823, 2015). "Combined, these studies suggest that changes that increase the potential for IGF1-IGF1R interaction (i.e., increased IGF1/IGF1R, decreased IGFBPs) promote ovarian cancer and that the IGF network is a promising therapeutic target." (PMID 25115504, 2014). "Conclusively, IGF1 could enhance the migration, invasion and EMT of ovarian cancer cells, and activated the PI3K-AKT and Wnt signaling pathways." (PMID 35964060, 2022). "Furthermore, they found that migracin A decreased insulin-like growth factor 1 gene (IGF-1) expression in ES-2 and JHOC-5 ovarian carcinoma cells." (PMID 35879795, 2022). "From the total of 34 ligand and receptor genes identified in these interactions, seven (COL1A1, ITGB5, COL1A2, FGFR2, FN1, IGF1, and IGF2) were consistently up-regulated and predicted worse overall survival in two additional cohorts (TCGA and GSE9891) of ovarian cancer patients." (PMID 36352420, 2022). "At the range of physiologically relevant concentrations, IGF-1 markedly induced HIF-1α and NOX4 expression levels in human ovarian cancer A2780 and OVCAR3 cells, thus HIF-1α might be one of the mechanisms regulating the expression level of NOX4." (PMID 34209278, 2021). "IGF-1 plays a key role in the development, maintenance and chemotherapeutic response of ovarian cancer, and serum concentrations of free IGF-1 were significantly increased in ovarian cancer patients." (PMID 34209278, 2021).
ovarian carcinoma (continued). "Knockdown of PON2 in ID8 cells (mouse ovarian cancer cells) also resulted in increased IGF-1 expression like that observed in SKOV3 cells (data not shown)." (PMID 29531225, 2018). "Hence, instead of directly targeting IGF-1/IGF-1R, which has adverse effect on glucose hemostasis, activating PON2 would be a fruitful alternative strategy for treating ovarian cancer." (PMID 29531225, 2018). "For example, heparin-binding EGF-like growth factor (HB-EGF), neuregulin-1 beta (NRG1β), insulin-like growth factor 1 (IGF1), and hepatocyte growth factor (HGF) are all expressed in tumors and found at higher levels in ascites fluid of ovarian cancer patients compared to healthy controls." (PMID 26648788, 2015). "More than 80% of the circulating IGF-1 pool originates from the liver, and thus, any secretory contribution from an ovarian cancer may be unlikely to influence endocrine IGF-1." (PMID 38396692, 2024). "In addition, insulin-like growth factor 1 (IGF1) expressed by TAMs increased the proliferation and migration of ID8 mouse ovarian cancer cells; while blockade of the IGF1 pathway in ID8 cells with an IGF1 neutralizing antibody effectively inhibited the ID8 caused tumor growth." (PMID 36035994, 2022). "After 21 days of induction with SFTG36 (SCF, FLt-3L, TPO, GM-CSF, IL-3 and IL-6), IS721 (IGF-1, SIS3, IL-7 and IL-21) and IL-15/Hsp70 media, NK cells phenotypes were studied and their cytotoxicity against K562 human erythroleukemia cells and SKOV3 ovarian carcinoma cells was analyzed." (PMID 34098947, 2021). "However, there is no information on the effects of adiponectin on IGF-1-induced proliferation in ovarian cancer cells." (PMID 29603059, 2018). "However, the role of IGF1 in the development of chemo-resistance in ovarian cancer has not yet been defined in patient cohorts that exhibit resistance to chemotherapy." (PMID 24237932, 2013). "The expression levels of six genes were found to be significantly elevated in ovarian cancer cells, except for FANCB and IGF1, which were not statistically significant." (PMID 40510161, 2025).